KLF1 (KLF transcription factor 1)
Diseases named in the same sentence as KLF1 in open-access papers (continued):
Sharing a sentence is not in itself a finding about the gene and the disease.
(CDA) type IV (3 papers, 2019 to 2025). "To test the generality of this phenomenon, we examined the E325K mutation in Klf1, which causes a dominant form of congenital dyserythropoietic anemia type IV." (PMID 40463169, 2025). "Mutations in KLF1 cause dyserythropoietic anemia congenital type IV (OMIM: 613673)." (PMID 30863397, 2019).
cervical cancer (3 papers, 2013 to 2024). A primary or metastatic malignant neoplasm involving the cervix. "For instance, KLF1 knockdown has been shown to suppress proliferation, metastasis, and invasion in cervical cancer cells." (PMID 39716068, 2024). "Knockdown of KLF1 expression has also been suggested to potentially inhibit the invasion and migration of cervical cancer cells by reducing the expression of Ki67." (PMID 39716068, 2024). "It has been reported that the expression of KLF1 enhanced the proliferation, migration and invasion of cervical cancer cells." (PMID 34304709, 2021). "Moreover, KLF1 is highly expressed in a variety of tumors, such as cervical cancer." (PMID 34304709, 2021). "The expression of KLF1 promoted the proliferation and EMT of cervical cancer cells by activating PI3K/Akt pathway." (PMID 34304709, 2021). "However, the expression of transcription factors for erythropoiesis, including GATA-1, KLF1, and SCL/TAL1, was not changed significantly in cervical cancer tissues compared to the controls (data not shown)." (PMID 23349856, 2013).
colorectal cancer (3 papers, 2022 to 2025). A primary or metastatic malignant neoplasm that affects the colon or rectum. "RBM15 has been shown to enhance the stability and expression of KLF1 mRNA in colorectal cancer through IGF2BP3-mediated m6A modification." (PMID 39716068, 2024). "Apart from that, overexpressing RBM15 could expedite colorectal cancer cell growth and migration by increasing KLF1 stability." (PMID 40883807, 2025). "In colorectal cancer, KLF1 expression is upregulated by RBM15 through m6A modification." (PMID 39716068, 2024). "In addition to KLF1, two hotspot mutations in KLF5 were found in colorectal cancer samples: one in DBD and another within a phospho-degron domain." (PMID 35996584, 2022). "Furthermore, previous studies have demonstrated that elevated RBM15 could accelerate colorectal cancer cell growth and metastasis through m6A modification of MyD88 and KLF1 mRNA." (PMID 40883807, 2025).
Congenital hemolytic anemia (3 papers, 2019 to 2021). A form of hemolytic anemia with congenital onset. "Hereditary hemolytic anemia could also be caused by mutations in Krüppel-like factor 1 (KLF1), a transcription factor controlling almost all aspects of erythropoiesis, although mutations in KLF1 can vary and lead to different phenotypes ranging from mild to severe phenotypes." (PMID 34831472, 2021).
gastric cancer (3 papers, 2023 to 2025). A primary or metastatic malignant neoplasm involving the stomach. "In gastric cancer, KLF1 overexpression promotes cancer cell migration and epithelial-mesenchymal transition (EMT)." (PMID 39716068, 2024). "The knockdown of KLF1 in gastric cancer inhibited the growth of tumor cells and the activation of the canonical WNT signaling pathway." (PMID 36761967, 2023). "Similarly, KLF1 significantly increased cell proliferation, transformation, and epithelial–mesenchymal transition in gastric cancer." (PMID 40798857, 2025). "Moreover, the Wnt/β-catenin pathway is suppressed by KLF1 silencing in gastric cancer, inhibiting migration and epithelial-mesenchymal transition of gastric cancer cells." (PMID 39716068, 2024). "Silencing KLF1 blocks the cell cycle of gastric cancer cells in the G1 phase." (PMID 36761967, 2023).
hereditary spherocytosis (3 papers, 2019 to 2022). Hereditary spherocytosis is a congenital hemolytic anemia with a wide clinical spectrum (from symptom-free carriers to severe hemolysis) characterized by anemia, variable jaundice, splenomegaly and cholelithiasis. "At a correlation cut-off of 0.8, a coexpression subnetwork of 26 GWAS-associated genes was centered on three known Mendelian genes causative for spherocytosis (SLC4A1, EPB42) and congenital anemia (KLF1)." (PMID 32888494, 2020).
Alzheimer disease (2 papers, 2017 to 2022). A progressive, neurodegenerative disease characterized by loss of function and death of nerve cells in several areas of the brain leading to loss of cognitive function such as memory and language. "The curated gene sets that showed most significant enrichment for our differentially methylated genes included a set of genes down regulated in erythroid progenitors from fetal liver in a mouse model knock-out of KLF1 and a set of genes upregulated in the brain of patients with Alzheimer’s disease." (PMID 34857913, 2022). "The analysis identified six significant gene sets at the diabetes studies and the combined datasets, including “UV response”, “chronic myelogenous leukemia”, “KLF1 targets”, “SMARCA2 targets”, “Alzheimer’s disease” and “stromal stem cells”." (PMID 28117714, 2017).
breast carcinoma (2 papers, 2021). "Moreover, some study revealed that KLF1 promoted the proliferation and invasiveness of breast cancer cells by activating the EMT process." (PMID 34304709, 2021). "However, the TFs such as KLF5 (52%), KLF1 (39%), and SMAD2::SMAD3::SMAD4 (31%) showed significant enrichment (q < 0.1) in gained peaks and FOX family of TFs (FOXA1 28%, FOXA2 28% and FOXF2 17%) in lost peaks in breast carcinomas." (PMID 34090364, 2021).
haemolytic anaemia (2 papers, 2021 to 2024). "For example, a study reported in 2021 revealed that four patients diagnosed with severe neonatal haemolytic anaemia carried compound heterozygous mutations of KLF1 gene." (PMID 38429690, 2024). "In recent years, some studies have found that homozygous or compound heterozygous class 2/3 mutation in KLF1 might contribute to severe haemolytic anaemia." (PMID 38429690, 2024).
heart failure (2 papers, 2023 to 2025). Inability of the heart to pump blood at an adequate rate to meet tissue metabolic requirements. "Our findings highlight the role of KLF1 in cardiomyocyte proliferation and cardiac regeneration and provide new insights for the treatment of MI and heart failure." (PMID 40145861, 2025). "In this study, the important role of Krüppel‐like factor 1 (KLF1) in cardiomyocyte proliferation and heart regeneration is explored, and revealed its ability to regulate the Wnt/β‐catenin signaling pathway as well as exploring a feasible strategy to target KLF1 for the treatment of heart failure." (PMID 40145861, 2025). "However, zebrafish with constitutive Klf1 expression exhibit heart failure-like symptoms and reduced survival, and only transient activation of Klf1 yields mature myocardium without pathological dilation." (PMID 37930405, 2023). "In conclusion, our findings highlight the role of the KLF1/Wnt/β‐catenin signaling pathway in cardiomyocyte proliferation and cardiac regeneration and suggest that the modulation of this pathway may be a potential therapeutic strategy for heart failure." (PMID 40145861, 2025).
hydrops fetalis (2 papers, 2019). Hydrops fetalis is a severe and challenging fetal condition usually defined as the excessive accumulation of fetal fluid within the fetal extravascular compartments and body cavities that manifests as edema, pleural and pericardial effusion and ascites. "Twenty‐five DEGs in both β‐thalassemia and SCD were also found in the published list of the DEGs in circulating erythroblasts from a homozygous KLF1‐null neonate with hydrops fetalis." (PMID 31134759, 2019).
lung carcinoma (2 papers, 2024 to 2025). "KLF1 is highly expressed in lung cancer cells, and downregulation of KLF1 inhibits the migration of NSCLC cells and induces apoptosis." (PMID 40798857, 2025). "In addition to KLF1, KLF13, KLF14 and KLF16 or KLF18 (?)with machine learning prediction waiting for verification, many KLFs have been found to be associated with the progress of lung cancer by activating or inhibiting target gene expression." (PMID 38560274, 2024). "However, up to now, whether some KLFs (KLF1, KLF13, KLF14 and KLF16) with unknown functions are involved in the progressions of lung cancer have not been fully understood, and remain to be explored or verified at the levels of cell, tissue and animal models." (PMID 38560274, 2024).
myelodysplastic syndrome (2 papers, 2018 to 2022). A clonal hematopoietic disorder characterized by dysplasia and ineffective hematopoiesis in one or more of the hematopoietic cell lines. "Many KLF1 target genes overlap with the expression signature identified in the differential analysis of myelodysplastic syndrome (MDS) patients that vary in their response to lenalidomide treatment." (PMID 29700354, 2018).
non-small cell lung carcinoma (2 papers, 2015 to 2025). A group of at least three distinct histological types of lung cancer, including non-small cell squamous cell carcinoma, adenocarcinoma, and large cell carcinoma. "Specifically, the lncRNA PCAT6 regulates the microRNA (miR)-326/ Krüppel-like factor 1(KLF1) axis in non-small cell lung cancer (NSCLC) cells." (PMID 40722682, 2025).
Arrhythmia (1 paper, 2024). Any cardiac rhythm other than the normal sinus rhythm. "Eight of these associations were novel (LMNA, SMAD6, HSPB9, TMEM95, KLF1, TET2, NME3, KDM5B) and 5 genes have previously been linked to arrhythmias (SCN5A, TTN, RPL3L, PKP2, PMVK)." (PMID 38390584, 2024).
atrial fibrillation (1 paper, 2024). A disorder characterized by an electrocardiographic finding of a supraventricular arrhythmia characterized by the replacement of consistent P waves by rapid oscillations or fibrillatory waves that vary in size, shape and timing and are accompanied by an irregular ventricular response. "Atrial fibrillation (ICD10 code I48) was associated with rare variation in 8 genes (TTN, RPL3L, KLF1, TET2, NME3, KDM5B, PKP2, PMVK)." (PMID 38390584, 2024). "Atrial fibrillation was associated with rare variations in 8 genes (TTN, RPL3L, KLF1, TET2, NME3, KDM5B, PKP2, PMVK)." (PMID 38390584, 2024).
autoimmune disease (1 paper, 2018). A disorder resulting from loss of function or tissue destruction of an organ or multiple organs, arising from humoral or cellular immune responses of the individual to their own tissue constituents. "These novel findings shed light on the understanding of PD-L1-mediated immune tolerance and suggest the potential therapeutic targeting of Klf1 and Egr2 in the treatment of autoimmune diseases and malignancies." (PMID 29728568, 2018). "Our findings indicate that Klf1 and Egr2 are modulators of PD-L1-mediated immune suppression in CD4+ T cells and might provide new insights into therapeutic targets for autoimmune diseases and malignancies." (PMID 29728568, 2018).
Bernard-Soulier syndrome (1 paper, 2025). Bernard Soulier syndrome (BSS) is an inherited platelet disorder characterized by mild to severe bleeding tendency, macrothrombocytopenia and absent ristocetin-induced platelet agglutination. "Genetic knock-out studies in Hoxa7-TPO cells recapitulate the key function of Klf1 and Nfe2 in red blood cell and platelet development, respectively, while disruption of the von Willebrand receptor gene Gp1ba recapitulates features of human Bernard-Soulier syndrome." (PMID 40775216, 2025).
cataract (1 paper, 2021). Partial or complete opacity of the crystalline lens of one or both eyes that decreases visual acuity and eventually results in blindness. "Consistent with previous report, the expression of KLF1 was also promoted in the lens capsule tissues of cataract patients compared to the normal people in this study." (PMID 34304709, 2021). "Results showed that the expression of KLF1 was enhanced in the lens capsules of cataract patients compared to the normal population." (PMID 34304709, 2021). "The expression of KLF1 in the lens capsules of cataract patients and normal populations was detected with the RT-PCR and western blotting." (PMID 34304709, 2021). "In this research, KLF1 was also found to promote the expression of ZBTB7A in lens capsule tissues of cataract patients and human lens epithelial cells." (PMID 34304709, 2021). "In addition, the results of oligonucleotide microarray hybridization experiment indicated that the expression of KLF1 was statistically significantly increased in the lens of cataract patients compared to the normal lens." (PMID 34304709, 2021). "Besides, the expression of KLF1 was elevated in the crystalline lens of cataract patients." (PMID 34304709, 2021).
Glomerular sclerosis (1 paper, 2022). Accumulation of scar tissue within the glomerulus. "Likewise, the extent of glomerular sclerosis, dilatation of Bowman's capsule and shrinkage of glomeruli in the renal corpuscles of Klf1K74R/K74R mice was also significantly lower than that in Klf1+/+ mice (9.24 ± 7.60% vs 24.53 ± 9.77%, p < 0.05)." (PMID 35822667, 2022).
hepatocellular carcinoma (1 paper, 2024). A malignant tumor that arises from hepatocytes. "As shown by the subcutaneous inoculation assay of Hepa1-6 cells, Klf1(K74R) mice also carry a higher anti-cancer capability against hepatocellular carcinoma than the WT mice." (PMID 38752723, 2024).
Hypertension (1 paper, 2022). The presence of chronic increased pressure in the systemic arterial system. "The measurements of systolic blood pressure (SBP) and diastolic blood pressure (DBP) in different age groups showed that the onset of hypertension or pre‐hypertension with advancing age was not yet observed in among the Klf1+/+ and Klf1K74R/K74R mouse groups." (PMID 35822667, 2022).
hypochromic anemia (1 paper, 2019). Anemia caused by the reduction of hemoglobin in relation to the red cell volume. "For example, compound heterozygotes of variants located in the zinc finger of the KLF1 gene may lead to microcytic hypochromic anemia." (PMID 31286593, 2019).
infarction (1 paper, 2025). A localised pathological necrosis of tissue resulting from obstruction of the blood supply usually by a thrombus, an embolus, or vascular torsion. "Through comprehensive in vivo and in vitro studies, it is demonstrated that in neonatal and adult mice, KLF1 overexpression significantly increased cardiomyocyte proliferation and promoted myocardial repair following infarction, whereas KLF1 knockout abolished these effects." (PMID 40145861, 2025).
juvenile myelomonocytic leukemia (1 paper, 2023). A myelodysplastic/myeloproliferative neoplasm of childhood that is characterized by proliferation principally of the granulocytic and monocytic lineages. "In the present study, evaluation of the KLF1 transcription unit in Juvenile Myelomonocytic Leukemia (JMML) samples enabled us to more precisely investigate the role of a conserved sequence in intron 1 in modulating expression of KLF1." (PMID 37165057, 2023).
liver cancer (1 paper, 2026). An epithelial or non-epithelial malignant neoplasm that arises from the liver. "Notably, in vitro experiments have shown that KLF1 enhances liver cancer cell proliferation by inhibiting ferroptosis, and this inhibition is negatively correlated with the transcription levels of fatty acid synthase 4 (ACSL4)." (PMID 41656392, 2026).
myeloid leukemia (1 paper, 2022). A clonal proliferation of myeloid cells and their precursors in the bone marrow, peripheral blood, and spleen. "Interestingly, previous evidence shows that HBG1, KLF1, and KLF3 are up-regulated in the β globin knockout human erythroid progenitor cell model, relative to controls and in human myeloid leukemia cells." (PMID 35627314, 2022).
myeloma (1 paper, 2020). "The master regulators of erythropoiesis, GATA1 and KLF1, were obviously downregulated in myeloma HSPCs." (PMID 33239656, 2020). "We also found that the expression of the transcription factors GATA1 and KLF1 was significantly downregulated in the HSPCs of myeloma patients, especially after the cells were co-cultured with bone marrow plasma from myeloma patients." (PMID 33239656, 2020). "In particular, the expression of the master regulators of erythropoiesis, including GATA1 and KLF1, was obviously decreased in myeloma CD34+ cells (FC < − 2.0, p < 0.01)." (PMID 33239656, 2020). "More importantly, the expression of transcription factors, such as GATA1 and KLF1, which govern erythrocyte differentiation, was significantly downregulated in CD34+ HSPCs from myeloma patients." (PMID 33239656, 2020).
myeloproliferative neoplasm (1 paper, 2018). A clonal hematopoietic stem cell disorder, characterized by proliferation in the bone marrow of one or more of the myeloid (i.e., granulocytic, erythroid, megakaryocytic, and mast cell) lineages. "Given that KLF1 levels may be playing a directive role in erythroid/megakaryocyte bipotential decisions, we focused on myeloproliferative neoplasms (MPNs) as cells whose aberrant properties might result from expression of mutated KLF1." (PMID 29700354, 2018).
myocardial infarction (1 paper, 2025). Gross necrosis of the myocardium, as a result of interruption of the blood supply to the area, as in coronary thrombosis. "This change may have been due to the low expression of KLF1 in cardiomyocytes during normal postnatal development but the significant upregulation of KLF1 expression following myocardial infarction in neonatal mice." (PMID 40145861, 2025). "However, Klf1 knockout severely decreased the proliferation of cardiomyocytes during the period of cardiac regeneration and led to incomplete cardiac regeneration and deteriorated cardiac function in mice that underwent myocardial infarction at P1." (PMID 40145861, 2025).
red blood cell disorders (1 paper, 2024). "KLF1 mutations have been found to cause different forms of anaemia and a range of red blood cell disorders, including various unrelated haemoglobin abnormalities." (PMID 38429690, 2024). "However, mutations in KLF1, which can be classified into four distinct groups, can result in a variety of red cell phenotypes and a wide range of red blood cell disorders." (PMID 38429690, 2024).
stem cell leukemia (1 paper, 2023). "In erythroid differentiation, core transcriptional networks play crucial roles, which include gata binding protein 1 (GATA1), T-cell acute lymphoblastic leukemia/stem cell leukemia (TAL1/SCL), Krüppel-Like Factor 1 (KLF1), LIM domain only 2 (LMO2), and LIM domain binding protein 1 (LDB1)." (PMID 37296674, 2023).